MYPOP (Myb related transcription factor, partner of profilin)
Description:
Transcriptional repressor; DNA-binding protein that specifically recognizes the core sequence 5'-YAAC[GT]G-3'. Dimerization with PFN1 reduces its DNA-binding capacity (By similarity).
Synonyms: P42POP
Tractability: No criterion of Open Targets' tractability assessment is met for any kind of drug.
Gene: Protein-coding gene on chromosome 19 (45,890,020 to 45,902,808, reverse strand). Ensembl gene ENSG00000176182.
Subcellular location: Nucleus
Subcellular location (Human Protein Atlas): Nucleoplasm
Gene Ontology:
Molecular function: protein binding; DNA-binding transcription factor activity, RNA polymerase II-specific; DNA-binding transcription repressor activity, RNA polymerase II-specific; RNA polymerase II cis-regulatory region sequence-specific DNA binding; DNA binding; DNA-binding transcription factor activity; identical protein binding
Biological process: negative regulation of transcription by RNA polymerase II; regulation of transcription by RNA polymerase II
Cellular component: nucleus
Genetic constraint (gnomAD): Loss-of-function variants: 17 observed, 14.48 expected, observed/expected ratio (o/e) 1.17, 90% interval 0.8 to 1.72. The synonymous counts are far from expectation, so gnomAD's model fits this gene poorly and the ratio says little. Missense variants: 507 observed, 406.24 expected, observed/expected ratio (o/e) 1.25, 90% interval 1.16 to 1.34. Synonymous variants: 251 observed, 172.66 expected, observed/expected ratio (o/e) 1.45, 90% interval 1.31 to 1.61.
Homologues: Orthologues: macaque MYPOP (99% identical), chimpanzee MYPOP (99% identical), pig MYPOP (89% identical), mouse Mypop (85% identical), guinea pig MYPOP (83% identical), rabbit MYPOP (72% identical), tropical clawed frog mypop (47% identical).
Diseases named in the same sentence as MYPOP in open-access papers:
MYPOP is named in the same sentence as 4 diseases in open-access papers, as found by Europe PMC text mining. Sharing a sentence is not in itself a finding about the gene and the disease. The quoted sentences say what the papers report.
cervical cancer (2 papers, 2018 to 2026). A primary or metastatic malignant neoplasm involving the cervix. "Here we show that in HPV-transformed cervical cancer cells, MYPOP induces alterations in cell morphology, silences viral and cellular oncogenes including E6 and MYC, and stimulates the release of the cancer-killing cytokine interleukin-24." (PMID 42156885, 2026). "Interestingly, total MYPOP amounts are strongly reduced in diverse HPV-transformed cell lines and cervical cancer, suggesting MYPOP downregulation as a precondition for oncogene expression, which is required for proliferation and finally tumor progression." (PMID 30018400, 2018). "Interestingly, we found that MYPOP protein levels are significantly reduced in diverse HPV-transformed cell lines and in HPV-induced cervical cancer." (PMID 30018400, 2018).
astrocytoma (1 paper, 2020). "From the 10 strongest associations, only TBPL1, MYPOP and BMP7 appeared to be differently expressed in astrocytoma, albeit not specific to only astrocytoma." (PMID 33057419, 2020).
tumor (3 papers, 2018 to 2026). "Collectively, our findings identify MYPOP as a selective suppressor of tumor cell proliferation across species in vitro and point to its potential relevance for future therapeutic investigation." (PMID 42156885, 2026). "Moreover, MYPOP expression is broadly diminished across multiple human cancers, and its re-expression by both DNA- and mRNA-gene transfer markedly suppresses tumor cell proliferation while sparing normal epidermal keratinocytes." (PMID 42156885, 2026). "Our results confirmed the roles of β‐catenin, SMAD2, and SMAD3 in promoting EMT, and identified the roles of tumor suppressor MYBBP1A, NKRF, and MYPOP in repressing the EMT process." (PMID 37566765, 2023). "The MYB-related transcription factor and partner of profilin (MYPOP or p42POP) is a ubiquitously expressed yet understudied protein recently identified as a restriction factor of oncogenic human papillomaviruses (HPV) and proposed tumor suppressor." (PMID 42156885, 2026). "Accordingly, overexpression of MYPOP resulted in a substantial decrease in the number of HPV16- or HPV18-immortalized and non-virally transformed keratinocytes, indicating that MYPOP is able to block proliferation of tumor cells." (PMID 30018400, 2018). "Moreover, overexpression of MYPOP blocks colony formation of HPV and non-virally transformed keratinocytes, suggesting that MYPOP exhibits tumor suppressor properties." (PMID 30018400, 2018).
cancer (2 papers, 2024 to 2026). A tumor composed of atypical neoplastic, often pleomorphic cells that invade other tissues. "Additional cancer-relevant transcriptional regulators higher in responders before vaccination include SP2, NFYC, AKNA, MYPOP, and ZNF652." (PMID 39450169, 2024).